HSF4 (heat shock transcription factor 4)
Diseases named in the same sentence as HSF4 in open-access papers (continued):
Sharing a sentence is not in itself a finding about the gene and the disease.
colorectal cancer (5 papers, 2021 to 2025). A primary or metastatic malignant neoplasm that affects the colon or rectum. "HSF4 binds to the MET promoter in colorectal carcinoma to enhance MET expression and promote tumor progression." (PMID 40004241, 2025). "HSF4 has been reported to promote tumor progression by enhancing MET expression in colorectal carcinoma cells." (PMID 40004241, 2025). "While HSF4 is known to be oncogenic in several cancer types, such as colorectal cancer, hepatocellular carcinoma, and lymphoma, our data suggested that HSF-dependent expression of SCAN-TFs could actually reduce oncogenic gene expression in tumors." (PMID 36982267, 2023). "HSF4 directly binds to the MET promoter and enhances its expression, thereby promoting tumor progression in colorectal carcinoma." (PMID 40004241, 2025). "We also found that HSF4 regulated MET expression in RCC, consistent with a previous report describing this interaction in colorectal carcinoma." (PMID 40004241, 2025). "In HCC, breast cancer, prostate cancer, lung cancer, esophageal squamous cell carcinoma (ESCC), and colorectal cancer (CRC), HSF2 and HSF4 are frequently dysregulated, while HSF1 is highly expressed across all these cancers." (PMID 39248163, 2024).
hepatocellular carcinoma (4 papers, 2021 to 2025). A malignant tumor that arises from hepatocytes. "A recent study showed that HSF4 expression was significantly upregulated in hepatocellular carcinoma (HCC) tissues, whereby targeting HSF4 reduced HCC cell growth and metastasis-associated phenotypes both in-vitro and in-vivo." (PMID 33807297, 2021).
pancreatic cancer (3 papers, 2023 to 2025). "For instance, the interaction between FGD3 and HSF4 can inhibit the expression of p65, thereby suppressing pancreatic cancer progression." (PMID 39881364, 2025). "Additionally, high expression levels of HSF4 have been shown to promote the progression of pancreatic cancer and CRC." (PMID 39881364, 2025).
prostate carcinoma (3 papers, 2023 to 2025). A carcinoma that arises from epithelial cells of the prostate gland. "We next examined whether the gene expression of SCAN-TFs (MZF1, SCAND1, and SCAND2(P)) was correlated with HSF1 or HSF4 gene expression in prostate cancer specimens derived from patients." (PMID 36982267, 2023).
viral infections (3 papers, 2008 to 2015). "In conclusion, we demonstrate that the hypersensitivity of Hsf 4 mutants to viral infections is accompanied by a modest increase in viral titers." (PMID 26234525, 2015). "HSF4 regulates the expression of HSPs in response to different cellular stresses, such as oxidants, heavy metals, elevated temperature, and bacterial or viral infections." (PMID 24637349, 2014). "As Hsf 4 mutant flies are more sensitive to infection and support mildly higher virus replication than control flies, our data suggest that the heat shock response contributes to resistance to viral infection." (PMID 26234525, 2015). "Next, we asked whether the increased sensitivity of Hsf 4 mutants to viral infections was accompanied by higher viral replication rates." (PMID 26234525, 2015). "Overall, no major differences were observed between wild-type and Hsf 4 mutant flies, indicating that inducible responses to virus infection are not regulated by the heat shock response, and that differences in survival of Hsf mutants cannot be explained by defects in known immune pathways." (PMID 26234525, 2015). "HSF4 (OMIM 602438) belongs to the family of heat shock transcription factors that regulate the expression of heat shock proteins in response to different cellular stresses, such as oxidants, heavy metals, elevated temperature, and bacterial or viral infections." (PMID 19014451, 2008).
breast carcinoma (2 papers, 2020 to 2024). "Since previous results had already indicated that HSF4 can modulate the expression of HIF-1α in MCF-7 breast cancer cells, it is possible that, similarly to HSF2, the function of HSF4 is hijacked in HCC in order to enhance HIF-1α expression, thereby allowing cancer progression." (PMID 32408596, 2020). "It remains to be elucidated whether HSF4 directly impacts breast cancer development." (PMID 32408596, 2020). "Nevertheless, both HSF4 and HSF2 have been indicated to modulate the expression of hypoxia-inducible factor 1-alpha (HIF-1α) in MCF-7 breast cancer cells." (PMID 32408596, 2020).
colon cancer (2 papers, 2023 to 2025). "HSF4 has already been reported to act in an inhibitory manner against apoptosis in colon cancer cells and lens formation, and our experiment revealed that it does the same in RCC by RNA sequencing and flow cytometry." (PMID 40004241, 2025). "In the present study, a four-gene signature of colon cancer, consisting of HSF4, UPK3B, ZNF767P, and AGAP9, was generated and validated." (PMID 36681801, 2023).
thyroid cancer (2 papers, 2019 to 2021). "In contrast, the expression of HSF4 was significantly lower in glioblastoma multiforme, ovarian cancer, testicular germ cell cancer, thyroid cancer, and uterine carcinosarcoma as compared to their respective normal tissues." (PMID 33807297, 2021). "Intriguingly, thyroid cancer patients who had high expression of HSF4 had a worse prognosis as compared to patients expressing a low level of HSF4." (PMID 33807297, 2021).
age (1 paper, 2008). A temporal measurement of the time period elapsed since an identifiable point in the life cycle of an organism. "We screened sequence variants of HSF4 in age-related cataract patients and the natural population from Shanghai, China." (PMID 18941546, 2008).
albinism (1 paper, 2020). A congenital disorder characterized by partial or complete absence of melanin pigment in the eyes, hair, or skin. "The genes identified for MAC were KMT2D, MAB2IL2, ALDH1A3; ASDA were KERA, PAX6, MYOC, TGFBI, and SLC4A11; congenital cataract were CRYBB2, EPHA2, HSF4 and BCOR; infantile nystagmus were CACNA1A and FRMD7; and albinism were OCA2, GPR143, HPS6 and SLC38A8." (PMID 32830442, 2020).
cervical cancer (1 paper, 2021). A primary or metastatic malignant neoplasm involving the cervix. "Whilst HSF4 transcriptionally activated HIF1a expression in HCC cells, HSF4 was reported to co-opt with HSF2 to repress HIF1a expression and subsequently inhibit the expression of HIF1a downstream target genes in breast and cervical cancer cells." (PMID 33807297, 2021).
colorectal adenocarcinoma (1 paper, 2021). The most common type of colorectal carcinoma. "The cBioPortal database was used to analyze the mutations of seven genes, which showed that E2F3, ETS2, HLF, HSF4, KLF4, MEIS2, and TCF7L1 were altered in 8, 8, 6, 6, 5, 9, and 6% of 524 colorectal adenocarcinoma patients separately." (PMID 34603375, 2021).
glioblastoma multiforme (1 paper, 2021). "Further analysis revealed that there was no significant overall survival difference between patients who had high or low expression of HSF4 in glioblastoma, ovarian cancer, testicular germ cell cancer, and uterine carcinosarcoma (data not shown)." (PMID 33807297, 2021).
HCMV infection (1 paper, 2025). "While the impact of HSF4 on HCMV infection is not known, experiments with recombinant adenoviral particles have demonstrated that HSF4 is able to directly bind an HSE on the CMV immediate‐early promoter, a strong promoter commonly used in plasmids for ectopic gene expression." (PMID 40457168, 2025).
lamellar cataracts (1 paper, 2022). "Interestingly, in human Hsf4 mutants that cause congenital lamellar cataracts, all known amino acid substitutions located in the DBD are dominant negative mutations because of the formation of dysfunctional heterotrimers in heterozygous cells." (PMID 37789386, 2022).
mental retardation (1 paper, 2023). "In previous work, we reported the absence of mutations in four genes (PAX6, PITX3, HSF4 and LIM2 genes) encoding for congenital cataract and expressed in the human brain in Tunisian families with cataract and mental retardation." (PMID 37179318, 2023).
microcephaly (1 paper, 2011). A congenital or acquired developmental disorder in which the circumference of the head is smaller than normal for the person's age and sex. "But for PITX3 and HSF4 genes although variations were absent in 50 ethnically matched control samples, there is no segregation between these detected polymorphisms and the studied phenotype (association between congenital cataract, mental retardation and microcephaly) in family F1." (PMID 22103961, 2011). "Until today no candidate gene has been reported responsible for such phenotypes: association between congenital cataract, MR and congenital cataract, MR and microcephaly, so we tried to focus on genes already described in ADCC and/or ARCC and expressed in the human brain (PAX6, PITX3 and HSF4)." (PMID 22103961, 2011).
myopia (1 paper, 2022). "Notably, Egr1, the most abundantly expressed IETF at the mRNA level which also upregulates at the protein level at 6 h PCS, is a negative regulator of myopia whose expression upregulates in the lens following selenite stress as well as Hsf4 and β1-integrin gene deletion." (PMID 36359852, 2022).
neuroblastoma (1 paper, 2011). Neuroblastoma (NB) is the most common solid, extracranial childhood tumor. "Therefore, the negative control exerted by DUSP26 on HSF4, altogether with the inverse correlation in the expression of these two proteins in neuroblastoma, may contribute to repress HSF4 activity in neuroblastoma and its potential crosstalk with HSF1." (PMID 24212658, 2011).
nuclear cataract (1 paper, 2019). A cataract (disease) that involves the lens nucleus. "One visible phenotype of the Hsf4 mutation is the persistence of nuclei related to the absence of DNase2β activity known to be associated with nuclear cataracts." (PMID 31243103, 2019).
Obesity (1 paper, 2024). Accumulation of substantial excess body fat. "While HSF4 has not yet been directly linked to obesity or metabolic dysfunction, HSF1, another Heat Shock Transcription Factor is known to promote adipocyte browning via mitochondrial regulation." (PMID 38781157, 2024).
prostate adenocarcinoma (1 paper, 2023). "HSP90AA1 gene expression was negatively correlated with the gene expression of MZF1(ZSCAN6), SCAND1, SCAND2, and HSF4 in prostate adenocarcinoma specimens." (PMID 36982267, 2023).
rectal cancer (1 paper, 2025). A primary or metastatic malignant neoplasm that affects the rectum. "Additionally, HSF4 expression was significantly higher in tumour tissues compared to normal tissues in both colon and rectal cancers." (PMID 39881364, 2025).
Wilms tumor (1 paper, 2021). An embryonal neoplasm characterized by the presence of epithelial, mesenchymal, and blastema components. "HSF4 could be used as a prognostic marker in CRC, while SIX2 might be a diagnostic and prognostic biomarker in Wilms’ tumor." (PMID 34178996, 2021).
cancer (10 papers, 2020 to 2025). A tumor composed of atypical neoplastic, often pleomorphic cells that invade other tissues. "Analysis of TCGA PanCancer genomic data revealed that HSF4 was rarely targeted by mutations in cancers." (PMID 33807297, 2021). "Several reports have also described the association between HSF4 and some types of carcinoma." (PMID 40004241, 2025). "Similar to HSF1, knocking out HSF4 delayed tumor development and cancer cell proliferation in a carcinogenesis mouse model." (PMID 40457168, 2025). "Among the members of the HSF family, HSF1, HSF2, and HSF4 are widely expressed in various cancers and tissues." (PMID 39248163, 2024). "Among the analyzed cancer types: bladder, uterine, esophagus, and stomach cancers had the highest frequency of HSF4 genetic alterations, which were about 3%–3.5% of all cases for each cancer type." (PMID 33807297, 2021). "With regards to the HSF4 expression level, this gene was found to be differentially expressed across different cancer types." (PMID 33807297, 2021). "We also comprehensively discuss the roles of HSF4 in health and diseases, particularly in lens cell development, cataract formation, and cancer pathogenesis." (PMID 33807297, 2021). "This original finding described the clinical relevance of HSF4 in cancer and showed that high expression of HSF4 correlates with advanced disease progression, cancer recurrence and poor patient survival." (PMID 32408596, 2020). "This review focuses on the expression patterns and functions of HSF1, HSF2, and HSF4 in specific cancer types, highlighting the mechanisms by which the regulatory functions of these transcription factors are modulated." (PMID 32408596, 2020). "In this review, we focus on the expression patterns and functions of HSF1, HSF2, and HSF4 in specific cancer types and on the key mechanisms regulating HSF-driven tumor progression." (PMID 32408596, 2020). "HSF4‐mediated RAD51 expression has not been evaluated in cancer, where elevated RAD51 expression is linked to poor prognosis, but has been demonstrated to counteract the accumulation of cataract‐promoting DNA damage in the lens." (PMID 40457168, 2025). "Considering that HSP27/HSPB1 and HSP90/HSPC have many pro-tumorigenic properties in different cancer types, it would be important to determine whether HSF4 plays a key role in regulating the expression of HSP27/HSPB1 and HSP90/HSPC in CRC." (PMID 32408596, 2020). "Importantly, HSF1 and HSF4 showed significantly higher expression in most cancer types." (PMID 39248163, 2024). "Considering that HSF1, HSF2, and HSF4 display multiple properties in cancer, which are either unique or common for each factor, or whether they act synergistically or antagonistically with each other, the need for new and improved agents targeting HSFs is significant." (PMID 32408596, 2020). "A number of these genes are known to be involved in cancer, including the downstream gene epidermal growth factor receptor (EGFR), the lncRNAs DSCR8 and ADARB2-AS1, and the TF heat shock factor 4 (HSF4)." (PMID 34228637, 2021). "Furthermore, HSF4 has been shown to be involved in the MET, extracellular signal-regulated kinase, and AKT pathways in cancer." (PMID 40004241, 2025). "In addition to the extensive involvement of HSF1 in cancer, both HSF2 and HSF4 have been shown to affect cancer cell proliferation and invasion, and altered expression of HSF5 is associated with several cancer types." (PMID 40457168, 2025). "Although both HSF-1 and HIF-1 are essential transcription factors for stress responses, a limited number of studies have reported that HSF family proteins, HSF2 and HSF4, promote transcription of HIF-1α and result in VEGFA expression in several cancer cell lines." (PMID 38081808, 2023).
cancer (continued). "Given the recent reports on other members of the HSF family influencing the growth and other properties of cancer cells, it will be important to conclusively map the genomic loci that are regulated by HSF2 and HSF4, either alone or in conjunction with HSF1 and other transcriptional regulators." (PMID 32408596, 2020).
tumor (9 papers, 2016 to 2025). "Our findings indicate that HSF4 expression levels are closely associated with tumour stiffness and positively correlated with poor prognosis in CRC patients." (PMID 39881364, 2025). "High HSF4 (heat shock transcriptional factor 4) expression was strongly associated with tumour stiffness and poor prognosis." (PMID 39881364, 2025). "Previous studies have illustrated that matrix stiffness can promote CRC progression and metastasis by upregulating tumor-related genes such as HSF4, activating lipolysis, and enhancing angiogenesis." (PMID 40867005, 2025). "The wound healing assay demonstrated that the migratory capacity of tumour cells was markedly impaired following HSF4 knockout." (PMID 39881364, 2025). "The correlation between HSF4 expression and CRC tumour stiffness and its association with poor prognosis prompted us to investigate further." (PMID 39881364, 2025). "HSF4 expression correlates closely with tumour stiffness and predicts poor prognosis in CRC patients, promoting CRC invasion and metastasis through EMT-related signalling pathways independently of collagen content." (PMID 39881364, 2025). "Results showed that HSF4 knockout reduced tumour size, and unexpectedly, the combination of HSF4 knockout and LOXL1 overexpression further reduced tumour proliferation." (PMID 39881364, 2025). "In this study, we showed that an ICI exerted stronger tumor-suppressive effects when used in combination with HSF4 knockdown in vivo." (PMID 40004241, 2025). "High HSF4 expression correlates closely with tumour stiffness and predicts poor prognosis in CRC patients." (PMID 39881364, 2025). "Our study revealed a strong association between the high expression of Heat Shock Transcription Factor 4 (HSF4) and increased tumour stiffness, indicating a poor prognosis." (PMID 39881364, 2025). "Given that HSF4 promotes tumour growth independently of collagen, we further explored the role of HSF4 and CAFs in the distant metastasis of CRC." (PMID 39881364, 2025). "To further assess the ECM environment of the tumours, we performed immunohistochemical staining to evaluate the expression of HSF4, LOXL1, MASSON, and α-SMA." (PMID 39881364, 2025). "To investigate how HSF4 promotes tumour growth in this context, we knocked out HSF4 in HCT116 cells and co-seeded with fibroblasts (CCD-18Co), followed by in vivo tumourigenesis experiments in nude mice." (PMID 39881364, 2025). "Secondly, although we have identified the critical role of HSF4 in tumour stiffness sensing and disease progression in CRC, the underlying molecular mechanisms and signalling pathways remain incompletely elucidated." (PMID 39881364, 2025). "When tumors were removed 2 weeks later, tumor growth was significantly suppressed in the group with the combination of HSF4 knockdown and ICI treatment compared with each treatment alone." (PMID 40004241, 2025). "To validate these findings across different datasets, we also analysed the GEO10950 dataset from 24 CRC patients and confirmed that HSF4 expression was elevated in tumour tissues compared to adjacent normal tissues." (PMID 39881364, 2025). "Furthermore, HSF4 knockdown combined with an ICI showed synergistic suppression of tumor growth in vivo." (PMID 40004241, 2025). "Furthermore, in tumor spheroid formation assays, the tumor mass formation abilities of HSF4-knockdown cells were significantly decreased compared with those of the parental cell lines." (PMID 40004241, 2025). "HSF4 plays a critical role in both the normal formation of the lens and the progression of tumours." (PMID 39881364, 2025). "Hence, there is a great need for comprehensive analyses of HSF2 and HSF4 expression in different tumor types." (PMID 32408596, 2020).